NOL7 (nucleolar protein 7)
Description:
Functions as part of the small subunit (SSU) processome, first precursor of the small eukaryotic ribosomal subunit that coordinates the first two steps of ribosome biogenesis in transcription of the primary transcript pre-RNA and pre-18S processing. During the assembly of the SSU processome in the nucleolus, many ribosome biogenesis factors, an RNA chaperone and ribosomal proteins associate with the nascent pre-rRNA and work in concert to generate RNA folding, modifications, rearrangements and cleavage as well as targeted degradation of pre-ribosomal RNA by the RNA exosome. This subunit is required for processing of the 5'-external transcribed spacer sequence (5'ETS) of the primary transcript pre-rRNA to yield the 18S rRNA. Also plays a role in maintaining early pre-rRNA levels, either by assisting in its transcription or stability.
Synonyms: C6orf90; NOP27; RARG-1; dJ223E5.2; PQBP3
Tractability: Small molecule: a structure with a bound ligand is known. PROTAC: UniProt records ubiquitination sites on it; ubiquitination databases record sites on it; its protein half-life has been measured.
Gene: Protein-coding gene on chromosome 6 (13,615,335 to 13,633,912, forward strand). Ensembl gene ENSG00000225921.
Subcellular location: Nucleus, nucleolus
Subcellular location (Human Protein Atlas): Mitotic chromosome; Nucleoli; Mitochondria
Gene Ontology:
Molecular function: protein binding; RNA binding
Biological process: maturation of SSU-rRNA; ribosomal small subunit biogenesis
Cellular component: nucleolus; small-subunit processome; nucleus
Genetic constraint (gnomAD): Loss-of-function variants: 26 observed, 26.35 expected, observed/expected ratio (o/e) 0.99, 90% interval 0.72 to 1.37. The upper end of that interval is the gene's LOEUF score, 1.37, which puts it in group 5 of 6, group 1 being the genes least tolerant of losing a copy. Missense variants: 262 observed, 222.83 expected, observed/expected ratio (o/e) 1.18, 90% interval 1.06 to 1.3. Synonymous variants: 112 observed, 98.46 expected, observed/expected ratio (o/e) 1.14, 90% interval 0.98 to 1.33.
Homologues: Orthologues: chimpanzee NOL7 (100% identical), macaque NOL7 (98% identical), pig NOL7 (88% identical), guinea pig NOL7 (87% identical), rat Nol7 (78% identical), mouse Nol7 (76% identical), zebrafish nol7 (30% identical), tropical clawed frog nol7 (29% identical).
Diseases named in the same sentence as NOL7 in open-access papers:
NOL7 is named in the same sentence as 21 diseases in open-access papers, as found by Europe PMC text mining. Sharing a sentence is not in itself a finding about the gene and the disease. The quoted sentences say what the papers report.
bladder carcinoma (1 paper, 2022). "In contrast, reduced NOL7 expression was related to favorable OS in bladder carcinoma (p < 0.05), KIRC (p < 0.01), ovarian cancer (p < 0.001), and READ (p < 0.001)." (PMID 36077008, 2022).
breast carcinoma (1 paper, 2022). "Furthermore, NOL7 protein expression was found to be significantly associated with disease progression in multiple cancers, including breast cancer, ovarian cancer, colon cancer, KIRC, HNSC, and LUAD." (PMID 36077008, 2022).
cervical squamous cell carcinoma (1 paper, 2022). A squamous cell carcinoma arising from the cervical epithelium. "However, NOL7 expression showed no significant change during disease progression in several cancers, including cervical squamous cell carcinoma (CESC), PAAD, skin cutaneous melanoma (SKCM), and uterine corpus endometrial carcinoma (UCEC)." (PMID 36077008, 2022).
colon cancer (1 paper, 2022). "Consistently, both gene and protein expression of NOL7 were upregulated, along with disease progression in various cancers, including colon cancer, LUAD, and HNSC." (PMID 36077008, 2022).
lung carcinoma (1 paper, 2024). "A previous study suggested that PQBP3/NOL7 knockdown did not significantly affect nucleolus or cell structure in H1299 human lung carcinoma cells, while they overexpressed PQBP3/NOL7-YFP and subsequently knocked down the protein by siRNA." (PMID 39103492, 2024).
melanoma (1 paper, 2023). A malignant, usually aggressive tumor composed of atypical, neoplastic melanocytes. "Another example would be NOL7, a recently identified gene with an oncogenic function in melanoma growth and evolution, found to play a role through the HIF-1α/NOL7/HRas/PI3K/AKT/ERK axis." (PMID 37047539, 2023).
ovarian serous cystadenocarcinoma (1 paper, 2022). A malignant serous cystic epithelial neoplasm arising from the ovary. "Meanwhile, dysregulated NOL7 expression was found to be closely related to pathological stage and prognosis in several cancers, including LIHC, ovarian serous cystadenocarcinoma (OV), and bladder urothelial carcinoma (BLCA)." (PMID 36077008, 2022).
cancer (4 papers, 2018 to 2024). A tumor composed of atypical neoplastic, often pleomorphic cells that invade other tissues. "Our findings in the present study that PQBP3/NOL7 inhibits senescence could provide a hint for determining how functional changes of PQBP3/NOL7 regulated by cancer-associated mutations of the human PQBP3/NOL7 gene could influence cancer pathogeneses." (PMID 39103492, 2024). "NOL7 is a candidate cancer suppressor that localizes to 6p23, a segment with frequent loss of heterozygosity (LOH) in many tumors." (PMID 29653596, 2018). "Currently, the effect of cancer-associated mutations on PQBP3/NOL7 functional changes has not been elucidated." (PMID 39103492, 2024). "Taken together, these results demonstrated that NOL7 expression could predict patient survival in several cancer types, especially ACC, KICH, KIRC, LIHC, LUAD, and OV." (PMID 36077008, 2022). "Given that PQBP3/NOL7 is a gatekeeper of cell aging in senescent or diseased cells, PQBP3/NOL7 is a potential therapeutic target for cancer, neurodegeneration, and aging." (PMID 39103492, 2024). "The present study revealed that NOL7 expression was significantly correlated with the infiltration levels of several types of immune cells, including B cells, CD8+ T cells, CD4+ T cells, macrophages, neutrophils, and DCs, in many cancers." (PMID 36077008, 2022). "Our study suggests that NOL7 might interact with HMGB1, thus functioning as a key mediator related to prognosis and the status of tumor immunity in cancers." (PMID 36077008, 2022).
neurodegenerative disease (2 papers, 2018 to 2024). A disorder of the central nervous system characterized by gradual and progressive loss of neural tissue and neurologic function. "In this study, we reveal that the nucleolar polyglutamine binding protein 3 (PQBP3; also termed NOL7), which has been linked to polyQ neurodegenerative diseases, regulates senescence as a gatekeeper of cytoplasmic DNA leakage." (PMID 39103492, 2024). "Though the role of PQBP3/NOL7 in other neurodegenerative diseases was beyond the scope of this study, it is important to address how other polyQ proteins affect the function of PQBP3/NOL7." (PMID 39103492, 2024). "As previously demonstrated for PQBP1 in the contexts of SCA1, HD, and AD, PQBP3/NOL7 could function as an additional hub molecule in common pathologies across multiple neurodegenerative diseases." (PMID 39103492, 2024).
tumor (2 papers, 2010 to 2022). "Our evidence suggests that like many of these oncogenes and tumor suppressors, NOL7 may have be regulated through its subcellular localization, and its targeting may be critically linked to its tumor suppressive activity." (PMID 20875127, 2010). "NOL7 is a candidate tumor suppressor that localizes to a chromosomal region 6p23." (PMID 20875127, 2010).
NOL7 also shares sentences with these, for which no sentence is quoted: adrenocortical carcinoma (1 paper); Alzheimer disease (1); glioblastoma (1); hepatocellular carcinoma (1); Huntington disease (1); ovarian carcinoma (1); sarcoma (1); skin cutaneous melanoma (1); spinocerebellar ataxia type 1 (1); spinocerebellar ataxia type-7 (1); uterine corpus endometrial carcinoma (1).